CXCL2 (C-X-C motif chemokine ligand 2)
Diseases named in the same sentence as CXCL2 in open-access papers (continued):
Sharing a sentence is not in itself a finding about the gene and the disease.
encephalomyelitis (1 paper, 2016). Inflammation of the brain and the spinal cord. "The previous studies found that CXCL2 expression was significantly induced in encephalomyelitis mouse model with chronic demyelination." (PMID 28066178, 2016).
endotoxemia (1 paper, 2024). "In a study using male and female rats, ethanol-fed female rats were found to have more severe liver injury as well as increased endotoxemia, lipid peroxidation, NF-kappa B activation, and upregulation of chemokines MCP-1 (CCL2) and MIP-2 (CXCL2)." (PMID 38370409, 2024).
enteritis (1 paper, 2026). Inflammation of the small intestine. "We assessed the impact of Atg16l1-deficiency on PUFA-induced CXCL1 (C-X-C motif chemokine ligand 1) expression, as this chemokine (besides CXCL2) was potently induced in our model system and contributes to enteritis in Gpx4+/-IEC mice." (PMID 41382985, 2026).
enteroviral infection (1 paper, 2013). "Analysis of the cytokine/chemokine-profile following enteroviral infection with a cytometric bead array and Q-PCR revealed an enhanced secretion of PanGRO (CXCL1, CXCL2 and CXCL3), IL8 and CCL5." (PMID 23305147, 2013).
eosinophilia (1 paper, 2022). "Our data suggest that ACh has distinct effects associated with fungal allergen-induced pulmonary inflammation, on the one hand, promoting ILC2 cytokine production and eosinophilia, and on the other hand, inhibiting neutrophilia via suppression of CXCL1 and CXCL2 expression." (PMID 35711456, 2022).
epilepsy (1 paper, 2022). A brain disorder characterized by episodes of abnormally increased neuronal discharge resulting in transient episodes of sensory or motor neurological dysfunction, or psychic dysfunction. "There is scarce information about the role of CXCL2 in patients and animal models of epilepsy." (PMID 35326336, 2022). "Here, we assessed the expression levels of CCL5, CXCL2 and CXCL12 in a KA-induced model of epilepsy." (PMID 35326336, 2022).
esophageal carcinoma (1 paper, 2023). A primary or metastatic malignant neoplasm involving the esophagus. "Similar correlations were observed in esophageal carcinoma, with CXCL1, CXCL2, CXCL3, and PPBP negatively correlated with EMT, CXCL5 and CXCL6 positively correlated with EMT, and CXCL8 not correlated with EMT." (PMID 37686093, 2023).
Fever (1 paper, 2025). Body temperature elevated above the normal range. "Indeed, CXCL2 also known as macrophage inflammatory protein-2, has previously been shown to act as an endogenous circulating pyrogen during early LPS-induced fever." (PMID 40534875, 2025).
fibrosarcoma (1 paper, 2022). A malignant mesenchymal fibroblastic neoplasm affecting the soft tissue and bone. "CD163-KO TAMs had decreased production of IL-6 and CXCL2 in comparison to WT TAMs in co-culture with MCA205 (mouse fibrosarcoma) cells." (PMID 36686729, 2022).
fungal keratitis (1 paper, 2015). "Our experiment confirmed that Dectin-1 in early period of innate immune in rat fungal keratitis can work through IL-1β, IL-6, CCL2, CXCL1, CXCL2 to recruit neutrophils and macrophages to participate anti-fungal immunity." (PMID 26427623, 2015). "Dectin-1 in early period of innate immune responses in rat fungal keratitis might work through IL-1β, IL-6, CCL2, CXCL1, CXCL2 to recruit neutrophils and macrophages to participate anti-fungal immunity." (PMID 26427623, 2015).
hemarthrosis (1 paper, 2025). Bleeding into the joints. "During the acute phase (day 3), all M1 markers were elevated in response to hemarthrosis (Il6, Il1β, Nos2, Cxcl2 and Il1r1), whereby Il6 and Nos2 were suppressed to baseline levels by rhFVIII and mFcFVIII alike, without effects on Il1β, Cxcl2 and Il1r1." (PMID 40388523, 2025).
hydronephrosis (1 paper, 2014). Collection of urine in the renal pelvis that results in dilatation of the renal pelvis and calyces. "In this regard, chemokines like CCL2/MCP-1, CCL5/RANTES, macrophage inflammatory protein-2 (CXCL2/MIP-2), and γ-interferon-inducible protein (CXCL10/IP-10) have been evaluated in experimental hydronephrosis." (PMID 24692841, 2014).
Hyperkeratosis (1 paper, 2023). Hyperkeratosis is a histopathological term defining a thickened stratum corneum and may be present in many different skin conditions, with many possible overlaps. "We observed a significant increase in inflammatory factors (such as TNF-α, IL-1β, CXCL1, CXCL2, CCL4, and TLR7) and exacerbates hyperkeratosis and keratosis in STAT3 mice." (PMID 37465147, 2023).
hyperlipidemia (1 paper, 2025). "Our research shows that in addition to producing neutrophil chemokines (e.g., CXCL2), hyperlipidemia‐induced metabolic reprogramming in monocytes enhances NETs release through regulatory metabolites, specifically LPC and LPA." (PMID 39853712, 2025).
hypertensive retinopathy (1 paper, 2022). Retinopathy due to hypertension. "We evaluated the expression levels of a series of chemokines (CXCL1, CXCL2, CXCL3 and CXCL5) and their receptor CXCR2 in Ang II-treated retinas to investigate the role of chemokines and their receptors in hypertensive retinopathy." (PMID 35981418, 2022).
infarction (1 paper, 2017). A localised pathological necrosis of tissue resulting from obstruction of the blood supply usually by a thrombus, an embolus, or vascular torsion. "The results from the present study identify suppression of myocardial CXCL2 and CXCL5 chemoattractant expression by 11β-HSD1 as a novel mechanism with potential for regulation of neutrophil recruitment to the injured myocardium following infarction." (PMID 28522730, 2017).
inflammatory skin disease (1 paper, 2021). Inflammatory skin disorders covers a broad category that includes many conditions ranging in severity, from mild itching to grave medical health complications These disorders are common in people of all ages and races. "Likewise, several chemokines, CCL3L1, CCL17, CXCL2, and selectin SELPLG, were upregulated at week 8 in CS and have been implicated in various inflammatory skin diseases." (PMID 34925353, 2021).
leukopenia (1 paper, 2023). "We also analyzed the integrated results of metabolomics and transcriptomics and found that MDBD could relieve leukopenia and alleviate bone marrow damage by targeting steroid biosynthesis and IL-17 signaling pathway, in which the key genes are Jun, Cxcl2 and Egr1." (PMID 37601071, 2023).
lung squamous cell carcinoma (1 paper, 2023). "One example of this is the association of higher CXCL2 expression with worse prognosis in patients with lung squamous cell carcinoma." (PMID 37686093, 2023). "Due to the participation of CXCL2 in these processes, it may result in worse prognosis in patients with lung squamous cell carcinoma." (PMID 37686093, 2023).
lymphadenitis (1 paper, 2023). Acute or chronic inflammation of one or more lymph nodes. "CXCL9/MIG, CCL20, CCL23, CXCL10/IP-10, CXCL1, CXCL2, and CXCL8 significantly declined in our cohort of EPTB (48 TB pleuritis and 57 TB lymphadenitis) patients at both time points." (PMID 36635313, 2023).
lymphoma (1 paper, 2022). A malignant (clonal) proliferation of B- lymphocytes or T- lymphocytes which involves the lymph nodes, bone marrow and/or extranodal sites. "In Compagno Lymphoma Statistics26, CXCL2 was overexpressed in DLBCL versus normal tissue with a fold change of 2.544 consistent with Alizadeh Lymphoma Statistics27." (PMID 35181719, 2022).
measles (1 paper, 2023). A highly contagious viral infection caused by the measles virus. "Transcriptomic analysis of peripheral blood mononuclear cells (PBMCs) from children with measles shows upregulation of mRNAs for IL-1β, CIAS-1/NLRP3, tumor necrosis factor (TNF)α, CCL4/MIP-1β, CXCL2/GRO-β, CXCL8, and TNFAIP3/A20 consistent with NF-κB signaling and inflammasome priming." (PMID 36851476, 2023).
meningioma (1 paper, 2021). A generally slow growing tumor attached to the dura mater. "The results showed yellow modules are negatively related to the degree of infiltration of resting mast cells in meningioma tissues, thus, genes such as MYC, CXCL2, CXCL8 and FOSL1 in the module, are inversely associated with the degree of mast cell infiltration." (PMID 34772393, 2021).
mesothelioma (1 paper, 2023). A usually malignant and aggressive neoplasm of the mesothelium which is often associated with exposure to asbestos. "Furthermore, IL-8 and CXCL2 along with argininosuccinate were significantly elevated in the plasma of patients whose mesothelioma had progressed within the first 2 months of ADI-PEG20 therapy, compared with patients demonstrating disease control." (PMID 37010783, 2023).
metabolic syndrome (1 paper, 2016). A cluster of metabolic risk factors for CARDIOVASCULAR DISEASES and TYPE 2 DIABETES MELLITUS. "The chemokine member CCL2 was highly expressed in adipose tissue and contributed to the cells becoming insulin resistant while CXCL2 (or MIP-2), encoding macrophage inflammatory protein 2-alpha (MIP2-alpha), was the main marker of inflammatory reaction in metabolic syndrome." (PMID 27551318, 2016).
metastasis (1 paper, 2023). The spread or migration of cancer cells from one part of the body (where they first appeared) to another. "CXCL2 was the CXCR2 ligand that was most frequently linked with lymph node metastasis status across cancer types." (PMID 37686093, 2023).
monocytopenia (1 paper, 2019). "PLAG significantly decreased plasma levels of the chemokine (C–X–C motif) ligand 1 (CXCL1), CXCL2, interleukin (IL)-6, and C-reactive protein (CRP), which were elevated consistently with the occurrence time of neutropenia, monocytopenia, and thrombocytopenia." (PMID 31752148, 2019).
MRSA pneumonia (1 paper, 2022). "MRSA pneumonia was associated with high concentrations in BALF of proinflammatory cytokines (TNF-α, IL-6) and chemokines (CXCL2, CXCL5)." (PMID 35972289, 2022).
Neisseria gonorrhoeae infections (1 paper, 2012). "In Neisseria gonorrhoeae infections, there were higher protein levels of IL-6, CXCL1 and CXCL2 in the vaginal secretions of BALB/c mice." (PMID 22848503, 2012).
Nephroblastoma (1 paper, 2022). An embryonal neoplasm characterized by the presence of epithelial, mesenchymal, and blastema components. "The expression of CX3CL1, CXCL14 and CXCL2 in nephroblastoma was significantly decreased." (PMID 35530333, 2022).
neurofibroma (1 paper, 2017). An intraneural or extraneural neoplasm arising from nerve tissues and neural sheaths. "Inhba, Cxcl2, Il1b, Clcf1, Lif, and Ccl5 were up-regulated in human neurofibroma SCs, and may justify further study." (PMID 28256556, 2017).
nocardiosis (1 paper, 2022). Nocardiosis is a local (skin, lung, brain) or disseminated (whole body) acute, subacute, or chronic bacterial infection. "CXCL2, which has potent neutrophil chemotactic activity, was rapidly and significantly upregulated in the lung within 24 h of infection, which indicated that neutrophils recruited by CXCL2 played an important role during pulmonary nocardiosis." (PMID 36352407, 2022).
nonalcoholic steatohepatitis (1 paper, 2023). "Our data mining found that hepatic CXCL2 mRNA expression was also markedly down-regulated in patients with nonalcoholic steatohepatitis (Supplementary 1)." (PMID 39619227, 2023).
oral mucositis (1 paper, 2018). Inflammation of the mucous membranes of any of the structures in the mouth. "By systematically evaluating the expression patterns of chemokines in radiation/chemical-induced oral mucositis, we found that CXCL2 was highly expressed, whereas cultured MSCs negligibly express the CXCL2 receptor CXCR2." (PMID 29445104, 2018).
Pain (1 paper, 2019). An unpleasant sensory and emotional experience associated with actual or potential tissue damage, or described in terms of such damage. "These various receptor-mediated events are directly dependent on the CXCL1 or CXCL2 concentration, and dysregulation of these processes e.g., in the pathogenesis of neuropathic pain could switch the cell phenotype." (PMID 31616413, 2019).
papilloma (1 paper, 2023). A benign epithelial neoplasm that projects above the surrounding epithelial surface and consists of villous or arborescent outgrowths of fibrovascular stroma. "In contrast, v-rasHa-initiated papillomas upregulated the expression of the Cxcr2 ligand Cxcl2 in comparison to intact skin or Ras/ΔNp63α carcinomas." (PMID 37638000, 2023).
pulmonary edema (1 paper, 2022). Accumulation of fluid in the lung tissues causing disturbance of the gas exchange that may lead to respiratory failure. "In airways, PAR2 activation induces constriction, increases lung vascular and epithelial permeability and pulmonary edema, triggers SubstanceP release and increases CXCL2 production." (PMID 39086962, 2022).
pulmonary fungal infections (1 paper, 2021). "Recently, a comparable population of pro-inflammatory Cxcl2+ AMs has also been reported in response to pulmonary fungal infections in mice." (PMID 34292313, 2021).
rectal adenocarcinoma (1 paper, 2021). "In rectal adenocarcinoma, four hub genes including CXCL1, CXCL2, CXCL3, and GNG4 were highly expressed at the gene and RNA levels." (PMID 34269159, 2021).
rectal cancer (1 paper, 2021). A primary or metastatic malignant neoplasm that affects the rectum. "Seven hub genes, including SAA1, AGT, GNG4, GAL, CXCL1, CXCL2, and CXCL3, were upregulated in rectal cancer tissues." (PMID 34269159, 2021). "Results from a variety of bioinformatics analyses suggest that hub genes (CXCL1, CXCL2, and CXCL3) could be significant biomarkers for the prognosis of rectal cancer." (PMID 34269159, 2021). "It has been found that has-miR-1-3p could be involved in the progression of rectal cancer by regulating CXCL1, CXCL2, and CXCL3." (PMID 34269159, 2021). "The fact that has-miR-1-3p targets three hub genes simultaneously (FDR <0.05) indicated that has-miR-1-3p could be involved in the progression of rectal cancer by regulating CXCL1, CXCL2, and CXCL3." (PMID 34269159, 2021). "Besides CXCL1, CXCL2, and CXCL3, we mined seven other hub genes related to rectal cancer, including SAA1, AGT, GNG4, SST, SSTR2, GAL, and CXCL12." (PMID 34269159, 2021). "In our study, we contend that has-miR-1-3p may affect the prognosis of rectal cancer by targeting CXCL1, CXCL2, and CXCL3." (PMID 34269159, 2021).
renal fibrosis (1 paper, 2024). A final common manifestation of a wide variety of chronic kidney diseases characterized by glomerulosclerosis and tubulointerstitial fibrosis. "In diabetic nephropathy-induced renal fibrosis, silencing of lncRNA Meg3 inhibited LPS-induced production of CCL-2 and CXCL-2 cytokines, which ameliorated renal fibrosis in mice." (PMID 39113708, 2024).
respiratory failure (1 paper, 2025). The significant impairment of gas exchange within the lungs resulting in hypoxia, hypercarbia, or both, to the extent that organ tissue perfusion is severely compromised. "Investigation of the compartment-specific functions of factors such as CXCL2 and osteopontin could identify potential therapeutic targets to mitigate AKI-induced respiratory failure." (PMID 40371645, 2025).
rosacea (1 paper, 2025). A chronic erythematous skin disorder that affects the face. "Research has demonstrated that CXCL8, CXCL1, and CXCL2 are significantly upregulated in patients with rosacea." (PMID 41431076, 2025).
RSV bronchiolitis (1 paper, 2025). "The plasma levels of CXCL2 in the RSV bronchiolitis group were significantly higher than those in the control group [2460.47 (1745.79, 3055.59) pg/mL vs. 217.12 (160.72, 440.89) pg/mL; P < 0.001]." (PMID 41360931, 2025).
streptococcal infection (1 paper, 2013). Any of the several infectious disorders caused by members of streptococcus, a genus of gram positive bacteria belonging to the family Streptococcaceae. "A functional role of CXC chemokines has been proposed in streptococcal infections and we have demonstrated that M1 protein is a potent stimulator of CXCL1 and CXCL2 production in the lung." (PMID 23951087, 2013). "Notably, administration of NSC23766 completely inhibited M1 protein-induced gene expression of CXCL1 and CXCL2 in alveolar macrophages, indicating that Rac1 activity mediates macrophage production of CXC chemokines in streptococcal infections." (PMID 23951087, 2013).
thyroid cancer (1 paper, 2024). "According to transcriptome sequencing, antitumor chemokine regulatory genes (CXCR3) were upregulated, and protumor chemokine regulatory genes (CCR3, CXCL1, CXCL2, CXCL3, CXCL8, and CXCR2) were downregulated after MWA in thyroid cancer." (PMID 38779358, 2024).
tick-borne encephalitis (1 paper, 2018). Tick-borne encephalitis is caused by an arbovirus of the Flaviviridae family (tick-borne encephalitis virus, TBEV), transmitted principally by the bite of the Ixodes ricinus tick. "Concentrations of IL-17A, IL-17F, IL-22, CXCL1, and CXCL2 in serum (S) samples obtained from tick-borne encephalitis patients on admission to hospital are shown horizontal axes and in cerebrospinal fluid (CSF) samples obtained simultaneously on vertical axes (expressed in pg/ml)." (PMID 29678185, 2018).
tongue squamous cell carcinoma (1 paper, 2019). A squamous cell carcinoma that arises from the tongue. "A bioinformatics analysis suggested that CXCL10 and CXCL2 were members of the key molecules of epithelia in tongue squamous cell carcinoma." (PMID 30847302, 2019).
ulcer (1 paper, 2018). "In summary, the transplantation of CXCL2-overexpressing MSCs promotes ulcer healing." (PMID 29445104, 2018).
uterine cancer (1 paper, 2019). Primary or metastatic malignant neoplasm involving the uterine corpus and/or the cervix. "A study in a mouse model of uterine cancer found that neutrophils largely resided within hypoxic foci, and the culture of uterine cancer cell lines in hypoxia led to the expression of potent neutrophil chemo-attractants; CXCL1, CXCL2, and CXCL5." (PMID 31461847, 2019).
vascular tumor (1 paper, 2024). "IHC scores of CXCL1、CXCL2、IL6、ABCC1、LRP、BCL2, vascular tumor thrombus, ascites cancer cells, maximum tumor diameter, neoadjuvant chemotherapy, and HE4 were included in the prediction model." (PMID 38509620, 2024). "As predictors, the immunohistochemical scores of CXLC1, CXCL2, IL6, ABCC1, LRP, BCL2, vascular tumor thrombus, ascites cancer cells, maximum tumor diameter, neoadjuvant chemotherapy, and HE4 were employed." (PMID 38509620, 2024). "Finally, the immunohistochemical scores of CXLC1, CXCL2, IL6, ABCC1, LRP, BCL2, vascular tumor thrombus, ascites cancer cells, maximum tumor diameter, neoadjuvant chemotherapy, and HE4 were employed." (PMID 38509620, 2024).
ventilator-associated pneumonia (1 paper, 2022). Serious INFLAMMATION of the LUNG in patients who required the use of PULMONARY VENTILATOR. "In a ventilator-associated pneumonia mouse model caused by Acinetobacter baumannii, AZM (10 or 100 mg/kg) reduced the neutrophil influx and the release of IL-1β, IL-6, and CXCL2 in BALF." (PMID 35972289, 2022).
viral meningitis (1 paper, 2019). Inflammation of the membranes surrounding the brain and spinal cord due to a viral infection. "Both, bacterial and viral meningitis additionally displayed significantly elevated concentrations of the cytokines CCL1, CCL19, CCL20, CXCL2, CXCL6, IFNγ, and IL16." (PMID 31727097, 2019).